CFLAR (CASP8 and FADD like apoptosis regulator)
Description:
Apoptosis regulator protein which may function as a crucial link between cell survival and cell death pathways in mammalian cells. Acts as an inhibitor of TNFRSF6 mediated apoptosis. A proteolytic fragment (p43) is likely retained in the death-inducing signaling complex (DISC) thereby blocking further recruitment and processing of caspase-8 at the complex. Full length and shorter isoforms have been shown either to induce apoptosis or to reduce TNFRSF-triggered apoptosis. Lacks enzymatic (caspase) activity.
Synonyms: CASH; Casper; CLARP; c-FLIP; FLAME-1; I-FLICE; MRIT; CASP8AP1; FLAME; FLIP; cFLIP; FLAME1; c-FLIPL; c-FLIPR; c-FLIPS
Tractability: Small molecule: a structure with a bound ligand is known. Antibody: the Human Protein Atlas places it where antibodies can reach. PROTAC: ubiquitination databases record sites on it.
Gene: Protein-coding gene on chromosome 2 (201,116,154 to 201,176,687, forward strand). Ensembl gene ENSG00000003402.
Subcellular location (Human Protein Atlas): Cytosol; Nucleoplasm; Plasma membrane; Nuclear bodies
Pathways (Reactome):
Programmed Cell Death: CASP8 activity is inhibited; Dimerization of procaspase-8; RIPK1-mediated regulated necrosis; Regulation by c-FLIP
Signal Transduction: Regulation of TNFR1 signaling; TRAIL signaling
Gene Ontology:
Molecular function: enzyme activator activity; protease binding; protein binding; cysteine-type endopeptidase activity; cysteine-type peptidase activity; death receptor binding; peptidase activator activity; protein-containing complex binding
Biological process: apoptotic process; negative regulation of extrinsic apoptotic signaling pathway; negative regulation of extrinsic apoptotic signaling pathway via death domain receptors; positive regulation of canonical NF-kappaB signal transduction; regulation of necroptotic process; death-inducing signaling complex assembly; extrinsic apoptotic signaling pathway via death domain receptors; macrophage differentiation; negative regulation of apoptotic process; negative regulation of myoblast fusion; positive regulation of neuron apoptotic process; regulation of skeletal muscle satellite cell proliferation; skeletal muscle atrophy; skeletal muscle tissue development; skeletal muscle tissue regeneration; skeletal myofibril assembly; cellular response to dexamethasone stimulus; cellular response to epidermal growth factor stimulus; cellular response to estradiol stimulus; cellular response to hypoxia; cellular response to insulin stimulus; cellular response to nitric oxide; negative regulation of cardiac muscle cell apoptotic process; negative regulation of cellular response to transforming growth factor beta stimulus; negative regulation of epithelial cell apoptotic process; and 11 more
Cellular component: caspase complex; cytoplasm; cytosol; death-inducing signaling complex; nucleoplasm; plasma membrane; ripoptosome; CD95 death-inducing signaling complex
Genetic constraint (gnomAD): Loss-of-function variants: 7 observed, 33.14 expected, observed/expected ratio (o/e) 0.21, 90% interval 0.12 to 0.4. The upper end of that interval is the gene's LOEUF score, 0.4, which puts it in group 1 of 6, group 1 being the genes least tolerant of losing a copy. Missense variants: 274 observed, 440.26 expected, observed/expected ratio (o/e) 0.62, 90% interval 0.56 to 0.69. Synonymous variants: 160 observed, 171.52 expected, observed/expected ratio (o/e) 0.93, 90% interval 0.82 to 1.06.
Homologues: Orthologues: chimpanzee CFLAR (99% identical), macaque CFLAR (96% identical), dog CFLAR (78% identical), pig CFLAR (75% identical), rabbit CFLAR (74% identical), rat Cflar (67% identical), mouse Cflar (66% identical), guinea pig CFLAR (54% identical), tropical clawed frog cflar (37% identical), zebrafish cflara (31% identical), Caenorhabditis elegans csp-2 (17% identical), Caenorhabditis elegans ced-3 (15% identical), and 5 more. Paralogues in human: CASP8 (24% identical), CASP10 (23% identical), CASP9 (16% identical), CASP2 (15% identical), CASP1 (14% identical), CASP3 (14% identical), CASP5 (13% identical), CASP6 (13% identical), CASP7 (13% identical), CASP4 (12% identical), CASP12 (11% identical), CASP14 (9% identical), and 4 more.
Diseases named in the same sentence as CFLAR in open-access papers:
CFLAR is named in the same sentence as 187 diseases in open-access papers, as found by Europe PMC text mining. Sharing a sentence is not in itself a finding about the gene and the disease. The quoted sentences say what the papers report.
breast carcinoma (45 papers, 1999 to 2025). "The strongest interaction result in relation to overall breast cancer risk was found between CFLAR‐rs7558475 and current smoking (ORint = 0.77, 95% CI: 0.67–0.88, pint = 1.8 × 10−4)." (PMID 28670784, 2017). "Indeed, analysis of data derived from breast cancer patients revealed that lower levels of CFLAR expression was linked to poor patient outcomes as measured by diminished overall survival and relapse-free survival." (PMID 34545139, 2021). "The protein product of CFLAR regulates apoptosis, thus it is possible that CFLAR genetic variants affect response to DNA damage caused by tobacco associated carcinogens and therefore modify breast cancer risk conferred by smoking." (PMID 28670784, 2017). "Using publicly available data to compare CFLAR (which encodes for c-FLIP) expression in tumors compared to normal tissue, we surprisingly observed that CFLAR expression was lower in breast cancer (BRCA) when compared to normal counterpart tissue." (PMID 34545139, 2021). "In support of these data, we found that diminished CFLAR expression (which functions to facilitate the survival of ECM-detached cells) is correlated with poor clinical outcomes in breast cancer patients." (PMID 34545139, 2021). "The strongest gene–environment interaction in relation to overall breast cancer risk was noted between rs7558475 located in the CASP8 and FADD like apoptosis regulator (CFLAR) gene and current smoking (pint = 1.8 × 10−4)." (PMID 28670784, 2017). "CFLAR mRNA expression is also lower in breast cancer when compared to normal counterpart tissue." (PMID 35954468, 2022). "DBC1 has been proposed as a co-factor for IKKβ that stimulates its kinase activity, promoting RelA phosphorylation and transcriptional activity towards target genes such as CFLAR (c-FLIP) and bcl-xl in breast cancer." (PMID 28350359, 2017). "c-Myc accumulation resulted from TAS4464 treatment in MCF7 (breast cancer) cells, similar to the finding in AML cell lines, and c-Myc knockout (c-Myc KO) decreased TAS4464-mediated molecular responses, such as NOXA induction, Caspase cleavage and transcriptional suppression of CFLAR." (PMID 33420360, 2021).
lung carcinoma (36 papers, 2011 to 2025). "We document the molecular docking analysis data of Flupenthixol and desmethylastemizole with the apoptotic regulator proteins CFLAR and TRAF2 linked to lung carcinoma for consideration." (PMID 34602774, 2021). "Indeed, an analysis of data derived from The Cancer Genome Atlas (TCGA) revealed an inverse correlation between the expression levels of oncogenes (HRAS and AKT1) and CFLAR in breast and lung cancer samples." (PMID 34545139, 2021).
melanoma (30 papers, 2011 to 2025). A malignant, usually aggressive tumor composed of atypical, neoplastic melanocytes. "According to our study, coexpression of CCR2, CFLAR, PRKCQ, and LINC00324 was associated with autophagy in melanoma." (PMID 34250091, 2021). "A recent study reported that down regulation of CFLAR could enhance the antitumor response of T cells and enhances the PD‐1 blockade efficacy in a melanoma tumor model." (PMID 39443755, 2024).
renal carcinoma (29 papers, 2013 to 2025). A carcinoma arising from the epithelium of the renal parenchyma or the renal pelvis. "All three genes, CFLAR, FAS, and FASLG, were significantly higher expressed in ccRCC compared with the other two renal cancer types." (PMID 31097685, 2019). "Moreover, analysis of public data on the expression levels of c-FLIP (CFLAR), CD95 (FAS/TNFRSF6), and CD95L (FASLG) revealed significantly higher expression of these three genes in ccRCC compared with other renal cancers." (PMID 31097685, 2019).
colorectal cancer (24 papers, 2009 to 2026). A primary or metastatic malignant neoplasm that affects the colon or rectum. "CFLAR, as an antiapoptotic protein, is a key gene regulator to inhibit TRAIL-induced apoptosis in colorectal cancer cells." (PMID 33506057, 2021). "This protein is up-regulated in human colorectal cancer and by interacting with the antiapoptotic protein Caspase 8 (CASP8) and FADD like apoptosis regulator (CFLAR, also known as c-FLIP), it plays a key negative role in apoptosis." (PMID 33233365, 2020).
glioblastoma (19 papers, 2011 to 2025). The most malignant astrocytic tumor (WHO grade IV). "CFLAR expression was detected in glioblastoma tissue samples." (PMID 36142793, 2022). "Induction of hypoxia in the A172 glioblastoma cell line results in the expression of CFLAR." (PMID 36142793, 2022).
hepatocellular carcinoma (18 papers, 2009 to 2025). A malignant tumor that arises from hepatocytes. "For example, paclitaxel elevates the level of miR-512-3p that targets an anti-apoptotic gene, FADD-like apoptosis regulator (CFLAR, also known as c-FLIP), suggesting that miR-512-3p is responsible for paclitaxel-induced apoptosis to a degree in hepatocellular carcinoma cells." (PMID 33066509, 2020).
pancreatic cancer (17 papers, 2010 to 2025). "Panc-1 was selected based on the literature evidence of efficient use of triptolide in pancreatic cancer at pre-clinical and clinical level [Ref] as well as CFLAR being reported as a therapeutic target for triptolide in Pancreatic cancer [ref]." (PMID 26121980, 2015). "Our results of siRNA mediated knock down and overexpression of CFLAR in pancreatic cancer cell lines further provides evidence of its involvement in chemo-sensitivity to triptolide." (PMID 26121980, 2015).
leukemia (16 papers, 2010 to 2024). A malignant (clonal) hematologic disorder, involving hematopoietic stem cells and characterized by the presence of primitive or atypical myeloid or lymphoid cells in the bone marrow and the blood. "Using a murine Cux1-deficient leukemia model and human cells, we establish that CUX1-deficient leukemia cells rely on elevated levels of CFLAR to evade apoptosis." (PMID 33931647, 2021). "Mechanistically, CUX1 deficiency directly alleviates CUX1 repression of the CFLAR promoter to drive CFLAR expression and leukemia survival." (PMID 33931647, 2021). "In order to investigate whether CUX1-deficient primary leukemic cells are more reliant on CFLAR, we sought to generate a CUX1-deficient leukemia model." (PMID 33931647, 2021). "Having established that CFLAR depletion triggers apoptotic cell death in U937 and THP-1 myeloid cancer cell lines, we sought to test the relevance of our findings in our Cux1-haploinsufficient murine leukemia model." (PMID 33931647, 2021).
gastric cancer (12 papers, 2010 to 2023). A primary or metastatic malignant neoplasm involving the stomach. "Most of the highest expressed circRNA genes in gastric cancer samples are also present in tumor-adjacent tissue (CFLAR, CORO1C, HIPK3, ASXL1 and SFMBT2)." (PMID 29109417, 2017).
lymphoma (11 papers, 2010 to 2022). A malignant (clonal) proliferation of B- lymphocytes or T- lymphocytes which involves the lymph nodes, bone marrow and/or extranodal sites. "We confirmed the correlation of IRF4 with LIMD1 and CFLAR in a panel of cell lines derived from lymphomas." (PMID 25207815, 2014). "Of note, CFLAR is also downregulated by shIRF4 in JiJoye cells (1.32 fold) in the microarray results, consistent with the results from GEO bioinformatics that IRF4 correlates with CFLAR in non-Hodgkin’s lymphomas and depletion of IRF4 downregulated CFLAR protein level in EBV+ lymphoma cells." (PMID 25207815, 2014). "The expression levels of both IRF4 and CFLAR were higher in ABC than those in GCB (investigated in the Lenz Lymphoma Statistics and Zhang Lymphoma Statistics datasets, respectively)." (PMID 29992138, 2018). "In addition, we have identified a panel of novel transcriptional targets including IFI27, IFI44, GBP1, CFLAR and ARHGAP18 for IRF4 in lymphomas." (PMID 25207815, 2014).
autoimmune disease (6 papers, 2010 to 2024). A disorder resulting from loss of function or tissue destruction of an organ or multiple organs, arising from humoral or cellular immune responses of the individual to their own tissue constituents. "Data from the literature show that CFLAR is also regulated by the IL-2 and MAPK pathway and that abnormal expression is related to some diseases, such as cancer and autoimmune diseases." (PMID 28719625, 2017).
B-cell lymphoma (6 papers, 2014 to 2023). "A pool of important genes involved in B-cell development, oncogenesis, cell cycle regulation, and cell death including BATF, LIMD1, CFLAR, PIM2, and CCND2 are common signatures associated with IRF4 in non-Hodgkin B cell lymphomas." (PMID 25207815, 2014).
Sepsis (5 papers, 2019 to 2024). Sepsis is defined as life-threatening organ dysfunction caused by a dysregulated host response to infection. "Survival analysis showed that PRKCD, EGLN1 and CFLAR were positively correlated with sepsis prognosis." (PMID 38997656, 2024). "Single-cell RNA sequencing has also revealed CFLAR expression on neutrophils in Sepsis patients’ blood." (PMID 37007944, 2023). "According to Sepsis single cell data, two genes, CFLAR and CASP4, were highly expressed in all immune cell subpopulations." (PMID 37007944, 2023). "We found that the CFLAR gene is likely to play a key role in glucose metabolism in Sepsis patients." (PMID 37007944, 2023).
Alzheimer disease (3 papers, 2017 to 2025). A progressive, neurodegenerative disease characterized by loss of function and death of nerve cells in several areas of the brain leading to loss of cognitive function such as memory and language. "The BCL3, CFLAR, SMAD1, and HIF1A genes have been identified to be associated with late-onset Alzheimer's disease." (PMID 28558704, 2017).
breast tumor (3 papers, 2011 to 2021). "Given the surprising evidence that CFLAR expression was diminished in breast tumors, we were interested in determining a biological rationale that could lead to such an outcome." (PMID 34545139, 2021). "Given the data suggesting that CFLAR expression is often downregulated in breast tumors, we reasoned that the introduction of oncogenic signals in non-cancerous mammary epithelial cells may block the ECM-detachment-mediated elevation in c-FLIPL." (PMID 34545139, 2021).
Stroke (3 papers, 2023 to 2025). Sudden impairment of blood flow to a part of the brain due to occlusion or rupture of an artery to the brain. "Theses result suggest that fat intake and lipid metabolism could also regulate the epigenetic traits and expression level of CFLAR in stroke patients." (PMID 39648651, 2024). "Flowchart illustrating the protective effect of zinc on stroke through various stages: GWAS analysis and NHANEs database, bioinformatic analysis, diagnostic model, pathway analysis showing autophagy, and genes involved (RELA, TNFSF10, NFE2L2, FADD, DDIT3, CFLAR)." (PMID 40969765, 2025). "The key genes encompass critical pathways such as autophagy (e.g. NFE2L2, DDIT3, NAMPT), apoptosis (e.g. CFLAR, FADD) and NF-κB signaling (e.g. RELA, TNFSF10), suggesting a multifactorial involvement of these pathways in stroke pathophysiology." (PMID 40969765, 2025). "However, overexpression of CFLAR could markedly alleviate cerebral I/R injury in MCAO mice by suppressing inflammation and ER stress, suggesting that variations of the autophagy-related DE genes might function to restore the damaged brain in CE stroke rather than the immediate ischemic injuries." (PMID 37305740, 2023).
cholesteatoma (2 papers, 2012 to 2015). A pathologic process characterized by the proliferation of keratinizing squamous epithelium resulting in the accumulation of keratin and cells in the middle ear and/or mastoid. "A down-regulation of cIAP1 (BIRC2) was observed, whereas p65 (RELA), cFlip (CFLAR) and Bcl-2 show similar expression levels in cholesteatoma and external auditory skin samples." (PMID 23285167, 2012).
Ewing sarcoma (2 papers, 2012 to 2013). A small round cell tumor that lacks morphologic, immunohistochemical, and electron microscopic evidence of neuroectodermal differentiation. "Importantly, successive steps allowed to identify novel players involved in Ewing sarcoma such as CUL1 or CFLAR or IER3." (PMID 23935076, 2013).
heart failure (2 papers, 2014 to 2024). Inability of the heart to pump blood at an adequate rate to meet tissue metabolic requirements. "As reported, CFLAR is a negative regulator of pathological cardiac remodeling and the resultant heart failure that was associated with its potential modulation of apoptosis, inflammation and fibrosis." (PMID 39450165, 2024). "CFLAR is a crucial component of the signaling pathway involved in cardiac remodeling and heart failure." (PMID 24564208, 2014).
myocardial infarction (2 papers, 2023 to 2024). Gross necrosis of the myocardium, as a result of interruption of the blood supply to the area, as in coronary thrombosis. "In post-myocardial infarction rodents, reduced CFLAR expression is observed in the ventricular myocardium, while CFLAR knockout mice display impaired cardiac trabeculae formation and myocardial thinning." (PMID 38956669, 2024). "There is evidence that reduced levels of CFLAR contribute to inflammation after myocardial infarction." (PMID 37007944, 2023).
non-alcoholic steatohepatitis (2 papers, 2020 to 2024). "Caspase 8 and FADD-like apoptosis regulator (CFLAR) has been identified as a potent factor in mitigating non-alcoholic steatohepatitis (NASH) by inhibiting the N-terminal dimerization of apoptosis signal-regulating kinase 1 (ASK1)." (PMID 39063139, 2024). "CFLAR is a key suppressor of non-alcoholic steatohepatitis in mice and nonhuman primates." (PMID 39063139, 2024). "Honokiol (HNK) has been reported to possess various beneficial effects in the context of metabolic disorders, including fatty liver, insulin resistance, and oxidative stress which are closely related to nonalcoholic steatohepatitis (NASH), however with no particular reference to CFLAR or JNK." (PMID 33354276, 2020).
non-Hodgkin lymphoma (2 papers, 2013 to 2014). Distinct from Hodgkin lymphoma both morphologically and biologically, non-Hodgkin lymphoma (NHL) is characterized by the absence of Reed-Sternberg cells, can occur at any age, and usually presents as a localized or generalized lymphadenopathy associated with fever and weight loss. "We have verified LIMD1 and CFLAR as two novel genes whose expression is correlated with IRF4 in non-Hodgkin lymphomas, and shown that CFLAR is likely an IRF4 target." (PMID 25207815, 2014). "Targeting CFLAR by IRF4 may implicate a role for IRF4 in Fas/TRAIL/TNFα-induced apoptosis in non-Hodgkin lymphomas." (PMID 25207815, 2014).